CD38 (CD38 molecule)
Diseases named in the same sentence as CD38 in open-access papers (continued):
Sharing a sentence is not in itself a finding about the gene and the disease.
tumor (continued). "The CD38+CD39+CD25-CD4+ TILs triggered increased tumor cell death." (PMID 36869048, 2023). "Moreover, a subset of CD8+ T cells that coexpress PD-1 and CD38 was only found in tumor tissues and was significantly upregulated as a result of IRAK3 deletion." (PMID 36757800, 2023). "CD3 ScFvs as well as ScFvs specific for several tumor-associated cell surface antigens such as CD19, CD20, CD33, B-cell maturation antigen (BCMA), CD123, and CD38, as well as for tumor antigens identified in hematological malignancies, have been generated for clinical application." (PMID 36831533, 2023). "Notably, CD11c+CD8+ T cells in tumor tissues had increased expression of CD38&HLA-DR, and PD-1, and decreased expression of GB, compared with those in peripheral blood and non-tumor tissues." (PMID 36798119, 2023). "On the basis of this, we proposed that these LRHG may control tumor invasion, with CD38 playing a key role in AN." (PMID 37188204, 2023). "Several studies suggest that daratumumab may induce tumor cell lysis in CD38-expressing tumors by CDC, ACDD, and ADCP." (PMID 36834545, 2023). "Consist with our findings, Zhu and colleagues concluded that CD38 could predict favorable prognosis in OV, by enhancing immune infiltration and anti-tumor immunity in tumor microenvironment." (PMID 37803446, 2023). "In addition, CD38 can also predict the prognosis of epithelial OV by enhancing immune infiltration and anti-tumor immunity in the microenvironment." (PMID 37415732, 2023). "Gene expression analysis of the tumor lesions for selected immune-related genes, confirmed a clear induction of markers associated with T cell activation and recruitment in SD101-treated mice (Perforin, Icos, Cd38, Ifng, Il2ra, Il7 and Cxcl10)." (PMID 37365634, 2023). "In the multivariate Cox regression analysis adjusted for other clinicopathological factors (age, tumor size, nodal status, and grading), CD38 was identified as an independent prognostic factor within the analyzed collective (HR 0.438, 95% CI 0.195–0.983; p = 0.045)." (PMID 37894900, 2023). "The enzymatic functions attributed to CD38 are primarily investigated in mouse and tumor models." (PMID 37419630, 2023). "Also, the impact of CD38 enzymatic activity on the immune system and tumor microenvironment still needs to be elucidated, besides participating in adenosine pathway." (PMID 38116009, 2023). "T cells and CD38+ primary tumor cells were isolated from the bone marrow of MM patients." (PMID 37039305, 2023). "Interestingly, combination treatment with guadecitabine/ICBs determined a significant increase of M1 (CD38+Egr2-) macrophages, respect to control and ICBs, indicating that triple therapy skews towards pro inflammatory anti-tumor TAM-M1 responses." (PMID 36934257, 2023). "Mechanisms of resistance against CD38 antibodies can be divided into tumor intrinsic resistance mechanisms, and immune microenvironment‐related resistance mechanisms, and numerous strategies are currently being investigated to overcome these resistance mechanisms." (PMID 37840445, 2023). "In addition, NAD-degrading enzymes, especially CD38, play critical roles in tumor cell immune evasion via the adenosinergic pathway." (PMID 38116009, 2023). "A proportion of TRM expressed an activated CD38+CD39+ phenotype within the tumor microenvironment." (PMID 36689623, 2023). "Thus, our results suggest that monocytes and macrophages armed with the tumor-targeting anti-CD38 IgE antibody would trigger antitumor activity in vivo." (PMID 37760502, 2023). "As MM is a tumor of Ab-producing PCs, precursors of PBs and PCs were identified by increased expression of CD38, decreased expression of CD45, and heterogenous (het) expression of CD19, CD20, CD27, and CD138 with surface membrane Igs (mIgs), such as IgA, IgG, and IgD." (PMID 36752202, 2023). "Moreover, activation of dendritic cells and frequency of CD38+ cytotoxic T cells in tumor tissues were significantly elevated by the PD-1 blockade in IRAK3-KO mice." (PMID 36757800, 2023).
tumor (continued). "We found a significantly higher frequency of CD38+PD-1+CD8+ T cell and CD38+PD-1+CD8+ TRM to be associated with HCC with higher histopathological grade III and IV, indicating that CD38 as a T cell co-exhaustion marker is also linked to tumor aggressiveness." (PMID 37377962, 2023). "In addition, CD38 is expressed on tumor-related immunosuppressive cells, including regulatory T and regulatory B cells and myeloid-derived suppressor cells." (PMID 36831262, 2023). "Indeed, we also found that the density of PD1+CD38+Tim3+ CD8+ T cells were significantly higher at the pre-BCG tumor tissues of BCG unresponsive tumors as compared to those who had no recurrence with BCG during the study period." (PMID 37566017, 2023). "To test whether this effect was specific to anti-CD20 mAb or more generally applicable as a means to increase NK cell activation in combination with tumour targeting mAb, we next investigated the anti-CD38 mAb daratumumab." (PMID 37528310, 2023). "On-target off-tumor toxicity should be considered when targeting CD38 with CAR T-cells." (PMID 37420216, 2023). "The tumor-targeting ability of anti-CD38-LNPs was also validated in a xenograft MM mouse model, where specific delivery of cytoskeleton-associated protein 5 (CKAP5) siRNA to bone marrow-residing and disseminated MM cells and improved therapeutic outcomes were achieved." (PMID 38516300, 2023). "Studies have reported that targeting CD38 attenuates tumor progression." (PMID 35725444, 2022). "Tumor cells were identified as CD38+, CD138+, CD19−, CD56+, CD269+, CD45+/−." (PMID 35454865, 2022). "Simultaneous targeting of CD38 on regulatory cells might contribute to a less immunosuppressive tumor milieu and to the expansion of effector T cells." (PMID 36405759, 2022). "CD38 might also play a role in the promotion of tumour growth via the suppression of effector T-cell responses in a tumour environment." (PMID 35784343, 2022). "In a clinical trial (NCT03367819), the combination of anti-CD38 (isatuximab) and PD-1 (cemiplimab) monoclonal antibodies in patients with mCRPC resulted in a median reduction of CD38+ tumor-infiltrating immune cells from 40% to 3% and the activation of peripheral T cells." (PMID 35892678, 2022). "CD38 enzymatic activity also leads to extracellular adenosine production, which is immunosuppressive and may contribute to immune system evasion by tumor cells." (PMID 35943588, 2022). "Isatuximab is a novel CD38-targeting antibody raised against a different epitope from daratumumab and is differentiated by the direct cytotoxic effect it can induce in tumors, as well as stronger inhibition of the tumor suppressive NADase role of CD38 in vitro." (PMID 36139103, 2022). "Furthermore, to model CAR-T cell-induced lysis of heterogenous populations of tumor cells, we mixed EGFR-expressing tumor cells with CD38-expressing tumor cells." (PMID 36531912, 2022). "CD38 bispecific antibodies can bind to CD38 on tumor cells and cytotoxic immune effector cells (T cells, a small number of NK cells), playing the antitumor role of the antibody itself and activating effector cells to attack tumor cells." (PMID 36313735, 2022). "Tumor-infiltrating CD38+ immune cells were reduced and almost cleared after treatment." (PMID 35987165, 2022). "The tumor cells in two cases expressed CD38 and CD138, indicating plasma cell differentiation." (PMID 35911381, 2022). "In the presence of IMiDs, isatuximab also induces enhanced direct cell apoptosis, augmented PBMC-mediated ADCC in MM cell lines and patient samples, and CD38 expression on Tregs was decreased, thus affording a further relief from the immunosuppressive tumor niche." (PMID 36139103, 2022). "CD38 is a transmembrane glycoprotein that functions both as a receptor and an ectoenzyme, playing key roles in the regulation of calcium signaling and migration of immune cells to tumor microenvironments." (PMID 35943588, 2022).
tumor (continued). "Tumor up-regulation of CD38 induced by all-trans-retinoic acid and interferon-β has been implicated in T-cell exhaustion and may represent a major mechanism of acquired resistance to immune checkpoint blockade therapy." (PMID 35987165, 2022). "CD38-CAR-T cells significantly reduced tumor growth and improved animal survival." (PMID 35765110, 2022). "Therefore, the role of CD38 in macrophage diseases, especially in tumor diseases, cannot be ignored." (PMID 35251964, 2022). "Antibody-mediated modulation of the enzyme function of CD38 may also contribute to changing a “cold” into a “hot” tumor microenvironment." (PMID 36405759, 2022). "In 2020, a North American team showed that α-particles combined with daratumumab reduce tumor growth in an animal model, but due to the possible down-modulation of CD38 on the surface of refractory cells, novel deep epitopes targetable by nanobodies have been recently investigated." (PMID 36009041, 2022). "In contrast, targeting of NK cells, as evidenced by a reduction of CD38-expressing NK cell numbers during daratumumab treatment may contribute to tumor relapse." (PMID 36405759, 2022). "This suggests that selectively targeting the enzyme activity of CD38 in the tumor microenvironment may be a strategy for treating solid tumors." (PMID 35906622, 2022). "Furthermore, anti-CD38 mAbs influence the tumor microenvironment by inhibiting suppressive Treg activity and boosting effector T-cell function." (PMID 36077708, 2022). "There is increasing evidence that CD38 is involved in tumor immune evasion; in particular, CD38 mRNA expression in mCRPC correlates with IL12, IL23, and IL27 signaling signatures as well as immunosuppressive adenosine signaling and T-cell exhaustion signatures." (PMID 35892678, 2022). "DARA is a humanized IgG1κ monoclonal antibody(mAb) that specifically binds to the epitopes of the cell surface of CD38, directly killing tumor cells through immune-mediated cytotoxicity, such as ADCC, CDC, and ADCP, and inducing apoptosis via FCγ receptor-mediated cross-linking." (PMID 36313735, 2022). "Therefore, CD38low/- NK cells play a significant role in the presence of CD38 mAb by inducing ADCC in the stressed tumor microenvironmental condition." (PMID 35342342, 2022). "Additionally, CD38+ tumor-infiltrating immune cell density has been shown to increase significantly in mCRPC tumors and correlate with poorer OS." (PMID 35892678, 2022). "It was found that, in AITL, patients expressing CD7 had a better prognosis, whereas patients expressing CD38 and Ki-67 had a poorer prognosis, It may suggest that tumor cells with more active proliferative capacity are more aggressive." (PMID 36466894, 2022). "In addition, inhibition of CD38 increases glutaminolysis in T cells and enhances their anti-tumor activity." (PMID 36248906, 2022). "Anti-CD38 antibody significantly prolongs survival time in tumor-bearing mice." (PMID 35725444, 2022). "In support of this hypothesis, it was recently shown that the CD38-NAD+-Sirt1 axis regulates immunotherapeutic anti-tumor T cell responses." (PMID 35281060, 2022). "These recent findings suggest that silencing CD38 (through methylation) may confer survival advantage to tumor-initiating progenitor cells or proliferative cancer cells by increasing NAD+ availability and mitochondrial function." (PMID 35677882, 2022). "The level of CD38 mRNA and protein was significantly increased on anti-PD-L1 resistant tumor cells." (PMID 35342342, 2022). "Other biomarkers such as chromosome instability, tumor microsatellite instability, and T-cell surface markers such as PD-11, CD38 and CD392, or tumor-infiltrating PD-1hi CD8+ T cells might serve as prognostic and predictive biomarkers for ICI therapy." (PMID 36119066, 2022). "This is likely due to cross-linking of CD38 on the tumor cell." (PMID 36405759, 2022).
tumor (continued). "They need a functional NAD+-Sirt1 Axis to exert an anti-tumor response, which research proved that the anti-CD38 antibody could enhance the inhibition of tumor." (PMID 35978433, 2022). "Collectively, the phenotypic features of tumor cells from the PDX were CD138+CD38+lambda+kappa-." (PMID 35992875, 2022). "Moreover, tumor-infiltrating CD38+ CD8+ T cells showed a pre-activated phenotype and expressed higher level of PD-1." (PMID 33934206, 2021). "As expected, due to prior daratumumab treatment, baseline CD38 expression on tumor cells was low." (PMID 34070044, 2021). "In these solid tumors, CD38 seems to be activated as a tumor-progressing factor." (PMID 33629216, 2021). "Daratumumab binds the CD38 molecule and mediates tumor cell killing through mechanisms including complement dependent cytotoxicity (CDC), antibody-dependent cellular phagocytosis, antibody-dependent cellular cytotoxicity (ADCC), and direct induction of tumor cell apoptosis." (PMID 33732154, 2021). "Our study suggest that increased CD38 expression defines tumor-infiltrating CD8+ T cells been pre-activated which involved in anti-tumor immunity through secreting cytotoxic molecule and also may function as the target cells of anti-PD-1 blockade." (PMID 33934206, 2021). "In addition, our results revealed that the capability of cell proliferation was notably restrained in all groups but CD38 WT and OE tumor cells showed a more significant inhibition than CD38 KO and MU tumor cells after treated tumor cells with ML385." (PMID 34226519, 2021). "We proposed that the functional impairment of CD38+ CD8+ T cells in tumor might be related to the occurrence of exhaustion." (PMID 33934206, 2021). "Escalated CD38 in TILs (CD38TILs) led to higher Ki-67 level of tumor cells." (PMID 34211854, 2021). "Over time, the immunosuppressive effect of highly CD38-expressing tumor cells may become dominant over the expression of PD-1 and PD-L1, resulting in resistance to treatment." (PMID 33467713, 2021). "Notably, transfer of daratumumab-CD38 complexes from tumor or normal cells to immune effector cells (trogocytosis) results in reduced levels of CD38 on the cell surface." (PMID 32457357, 2021). "Indeed, mouse models have previously shown improved anti-tumor activity when a CD38-targeting antibody is combined with PD-1 neutralizing antibody in a CD38-targeting antibody naïve setting." (PMID 34070044, 2021). "Therapeutic efficacy of 177Lu-DTPA-2F8 was assessed in mice bearing CD38+ RPMI 8226 tumours." (PMID 34727950, 2021). "Herein, we aimed to investigate whether tumor expressed CD38 could affect the proliferation, progression, and metastasis in vitro and in vivo." (PMID 34226519, 2021). "In the tumor microenvironment, CD38 and PD-1 in T-cells are upregulated by TGF-β." (PMID 34070758, 2021). "CD38-targeting MoAb such as DARA have been shown to cause complement-dependent cytotoxicity (CDC), antibody-dependent cellular cytotoxicity (ADCC), antibody-dependent cellular phagocytosis (ADCP), and tumor cell apoptosis." (PMID 33922005, 2021). "CD38 inhibition led to metabolic reprograming of T cells with superior tumor control." (PMID 34987512, 2021). "Strikingly, CD38 in HNSCC tumor tissues was positively related to immune checkpoint molecules." (PMID 34211854, 2021). "It was found that both 8-Br-cADPR and 78C (an enzyme inhibitor of CD38) could significantly inhibit tumor growth and tumor mass in CD38 WT-LLC-tumor-bearing mice while no therapeutic effects were observed in CD38 KO mice." (PMID 34226519, 2021). "As a result of these pleiotropic immune modulation, CD38 antibodies also enhance anti-tumor activity of others anti-cancer drugs with several studies highlighting that CD38-targeting antibodies have strong synergistic activity, such as combination to lenalidomide as well as to PD1/PD-L1 inhibitors." (PMID 34093594, 2021). "Herein, our results demonstrated that CD38 might use cADPR to influence cytoplasmic calcium concentration of tumor cells." (PMID 34226519, 2021).
tumor (continued). "Furthermore, we found that the positivity of CD38 was highly correlated with PD-1 positivity, suggesting CD38 as an additional marker of exhausted tumor-infiltrating T cells." (PMID 33747957, 2021). "Furthermore, the present study provides new insight into CD38 immunosuppression, suggesting the inhibited immune function of CD38 was affected not only by tumor microenvironment but also through circulating lymphocytes." (PMID 34211854, 2021). "Moreover, PD-1+ subset in tumor-infiltrating CD38+ CD8+ T cells expressed higher level of activated markers than PD-1+ CD38− CD8+ T cells." (PMID 33934206, 2021). "Furthermore, through co-cultivation with A549, we directly proved that tumor-infiltrating CD3+ CD+ T cells have a more strong tumor-killing capacity than tumor-infiltrating CD38− CD+ T cells in vitro." (PMID 33934206, 2021). "Thus, reinforcing the importance of CD38 mediated NAADP inhibition in the activity of tumor-promoting components of the TME." (PMID 33727923, 2021). "Furthermore, treatment with SFV/IFNg inhibited CD11b+ cell infiltration and decreased the CD206+ and CD38+ cell populations, explaining the observed inhibition of tumor growth." (PMID 34835178, 2021). "In this way, CD38 could contribute to the generation of a tumor-favorable environment, as recently demonstrated in tumors characterized by a large T cell infiltrate." (PMID 34421911, 2021). "The pretreatment expression of CD38 was correlated with a better outcome to daratumumab, while lack of response and tumor progression was associated with expression of both CD55 and CD59." (PMID 34299097, 2021). "Conversely, even though CD34+ CD38+ cell-surface antigen cells were highly detected in the tumor they couldn’t engraft new neoplasms." (PMID 34359786, 2021). "In solid tumors, CD38 is involved in immune evasion and tumor progression." (PMID 33467713, 2021). "Further, we examined whether apoptosis was induced by 5,6-ECs in non-tumor CD38–/CD138– BMNCs sub-population from patient P5." (PMID 34359648, 2021). "Furthermore, CD38, when expressed on tumor cells, can inhibit CD8+ T cells via adenosine production and the activation of adenosine receptor signaling on T cells." (PMID 33467713, 2021). "Furthermore, using a co-cultured experiment in vitro, we found that tumor-infiltrating CD38+ CD8+ T cells had a stronger tumor-killing effect than CD38− CD8+ T cells." (PMID 33934206, 2021). "In CLL, CD38 is a marker of both poor prognosis and aggressive tumor phenotype." (PMID 33467713, 2021). "High CD38/CD101 co-expression by PD-1+ CD8+ T cells in the peripheral blood of PCa patients or tumor-infiltrating lymphocytes (TILs) in PCa tissues correlated significantly with tumor/node/metastasis (T/N/M) classification, and with clinical stage and survival." (PMID 34439378, 2021). "First, the cytolytic effects of CD38 CAR-T cells on tumor cells were analyzed by luciferase assay." (PMID 34513682, 2021). "In conclusion, our findings suggest that selectively targeting the enzymatic activity of CD38 in tumor microenvironment might represent an important strategy in treating non-hematopoietic cancers." (PMID 34226519, 2021). "The role of CD38 is not completely understood in tumor immunology, but overexpression might indicate suppressive mechanisms to control an over-activated immune system." (PMID 34360781, 2021). "The hypothesis of this study was that the enzymatic activities of CD38 was essential in mediating cell survival and metastasis in tumor microenvironment." (PMID 34226519, 2021). "In a study of 94 patients with NKTCL, 95% of tumor samples expressed CD38 and clinical data suggested that CD38 may be a novel prognostic biomarker." (PMID 33588922, 2021). "The failure of anti-PD-1 antibody may stem from the elevated CD38 expression in the long-established tumor immune microenvironment." (PMID 34930285, 2021). "The synergistic binding might contribute to the enhanced cytotoxicity of BM38 CAR-Ts to BCMA+ CD38+tumor cells." (PMID 34627333, 2021).